NUDT8 (nudix hydrolase 8)
Description:
Acyl-CoA diphosphatase that mediates the hydrolysis of a wide range of CoA and CoA esters yielding 3',5'-ADP and the corresponding 4'-phosphopantetheine derivative as products (By similarity). Hydrolyzes short- and medium-chain acyl-CoAs, exhibiting the highest activity toward free CoA, hexanoyl-CoA, and octanoyl-CoA and the lowest activity against acetyl-CoA (By similarity). Exhibits decapping activity towards dpCoA-capped RNAs in vitro (By similarity).
Synonyms: FLJ41567
Tractability: PROTAC: ubiquitination databases record sites on it.
Gene: Protein-coding gene on chromosome 11 (67,627,937 to 67,629,937, reverse strand). Ensembl gene ENSG00000167799.
Subcellular location: Mitochondrion
Subcellular location (Human Protein Atlas): Nucleoli; Cytosol
Pathways (Reactome):
Metabolism: Vitamin B5 (pantothenate) metabolism
Gene Ontology:
Molecular function: coenzyme A diphosphatase activity; magnesium ion binding; manganese ion binding
Biological process: acetyl-CoA catabolic process; butyryl-CoA catabolic process; coenzyme A catabolic process; malonyl-CoA catabolic process; medium-chain fatty-acyl-CoA catabolic process; propionyl-CoA catabolic process; succinyl-CoA catabolic process
Cellular component: mitochondrion
Genetic constraint (gnomAD): Loss-of-function variants: 13 observed, 11.31 expected, observed/expected ratio (o/e) 1.15, 90% interval 0.75 to 1.76. The upper end of that interval is the gene's LOEUF score, 1.76, which puts it in group 6 of 6, group 1 being the genes least tolerant of losing a copy. Missense variants: 326 observed, 282.58 expected, observed/expected ratio (o/e) 1.15, 90% interval 1.05 to 1.26. Synonymous variants: 160 observed, 140.01 expected, observed/expected ratio (o/e) 1.14, 90% interval 1 to 1.3.
Homologues: Orthologues: chimpanzee NUDT8 (100% identical), macaque NUDT8 (96% identical).
Diseases named in the same sentence as NUDT8 in open-access papers:
NUDT8 is named in the same sentence as 1 disease in open-access papers, as found by Europe PMC text mining. Sharing a sentence is not in itself a finding about the gene and the disease. The quoted sentences say what the papers report.
cancer (2 papers, 2017 to 2019). A tumor composed of atypical neoplastic, often pleomorphic cells that invade other tissues. "Thus, we show that NUDT8 is likely to have a role in cancer, whose experimental validation will be the subject of a future study." (PMID 30778056, 2019). "However, a distinct cluster appeared when comparing cancer vs normal tissues, which contained NUDT1, NUDT5, NUDT8, NUDT14, and NUDT22, confirming a potential role of these NUDIX hydrolases in cancer." (PMID 29142246, 2017).